AR (androgen receptor)
Diseases named in the same sentence as AR in open-access papers (continued):
Sharing a sentence is not in itself a finding about the gene and the disease.
prostate carcinoma (continued). "Therefore, our findings elucidate an intracellular molecular mechanism that promotes prostate cancer lineage plasticity and suggest that UHRF1 may serve as a potential therapeutic target for overcoming resistance to AR-targeted therapies." (PMID 41760602, 2026). "In addition, SKP2 interacts with pRB, PTEN, AR, and H-RAS in prostate cancer." (PMID 41542047, 2026). "Additionally, adopting methods from prostate cancer research, such as CUT&RUN/ChIP for AR and co-regulators as well as quantitative nuclear-localization metrics, could capture pathway competence, not just expression." (PMID 41596366, 2026). "Similarly, in vivo studies demonstrated Bobcat339’s capacity to inhibit the growth of MSKPCa1 and DU145, an LKB1-negative/AR-negative prostate cancer cell line." (PMID 39743630, 2025). "Moreover, androgen receptor-negative prostate cancer cells PC-3 and DU145, estrogen-receptor positive breast cancer cells MCF7 and triple-negative breast cancer cells MDA MB 231 were also sensitive to Super-EBS." (PMID 39781466, 2025). "By contrast, p300 is dispensable in AR-negative prostate cancer cell lines (PC3 and DU145)." (PMID 41044247, 2025). "Notably, this combinatorial treatment is effective in prostate cancer cells regardless of AR status." (PMID 41046255, 2025). "By physically interacting with both the AR and the TIP60 complex in the cytoplasm, ING3 directs HAT activity to the immediate vicinity of the AR, enhancing AR activation and nuclear translocation, resulting in the development and progression of prostate cancer." (PMID 40149370, 2025). "In mice lacking AR in macrophages, reduced M2 polarization led to decreased eosinophil recruitment and lung inflammation, highlighting the critical role of androgen/AR signaling in regulating macrophage polarization in diseases like asthma and prostate cancer." (PMID 40438106, 2025). "Future testosterone GWAS should continue to explore the potential link between testosterone and dementia and prostate cancer, which may involve changes in androgen receptor signaling rather than androgen levels." (PMID 40316537, 2025). "Additionally, they demonstrated that androgen stimulation in melanoma cells did not significantly affect genes typically regulated by AR in prostate cancer, indicating that AR drives a distinct transcriptional program in melanoma cells." (PMID 40940929, 2025). "These experiments demonstrate that SH-BC-893 reduces nuclear levels of prostate cancer drivers MYC and the AR by triggering PP2A-dependent proteasomal degradation and blocking KPNB1-mediated nuclear import in parallel, redundancy that could limit the development of drug resistance." (PMID 40588551, 2025). "The tumor evolution leading to castration-resistant prostate cancer is accompanied by acquiring DNA mutations including mutations in the ligand binding domain (LBD) of the AR, amplification of AR, or non-classic activation of AR signaling that overcome inhibition by AR antagonists." (PMID 40072554, 2025). "Therefore, we suspect that the pioneer factor nature of GATA2 for AR observed in prostate cancer cells does not apply to the mesonephric mesenchyme during WD development." (PMID 40196482, 2025).
prostate carcinoma (continued). "Apalutamide, an oral selective androgen receptor inhibitor that directly binds to the ligand-binding domain of the androgen receptor, is FDA-approved for treating patients with nonmetastatic castration-resistant prostate cancer or metastatic castration-sensitive prostate cancer." (PMID 40051628, 2025). "However, since none of the compounds exhibits significant activity on androgen receptor signaling, their direct therapeutic potential for prostate cancer remains limited." (PMID 40429793, 2025). "This is particularly pertinent to patients with advanced prostate cancer, who are currently treated with hormone-deprivation therapies (ADT) and/or drugs interfering with either the transcriptional activity of the androgen receptor (AR), referred to as (ARIs), or the synthesis of androgens." (PMID 39858071, 2025). "Additionally, we examined the effects of RSPO2 overexpression in both androgen receptor-positive (AR+) and androgen receptor-negative (AR-) prostate cancer cell lines." (PMID 40711886, 2025). "To determine which ADP-ribosyl-Cys sites are responsible for PARP7-mediated AR degradation, we used a panel of ten AR mutants with amino acid substitutions (Gly, Ser) for Cys sites shown by mass spectrometry to undergo androgen-induced ADP ribosylation in prostate cancer cells." (PMID 40681873, 2025). "Disruption of the AR/filamin A complex using a stapled peptide effectively reduces CAF invasiveness and tumor growth in co-culture models, suggesting the potential for targeting this complex as a therapeutic strategy to enhance treatment outcomes in prostate cancer." (PMID 40008000, 2025). "Notably, both taxanes maintained efficacy regardless of AR expression status, highlighting their value in diverse prostate cancer phenotypes." (PMID 41038711, 2025). "The androgen receptor of prostate cancer is similar to the estrogen receptor in breast cancer, which may activate the cyclin D-CDK4/6, driving the proliferation of prostate cancer and resistance to hormone manipulation.Therefore, this has stimulated the search for CDK4/6 inhibitors." (PMID 41200193, 2025). "This could again be due to the fact that some of these agents only target the activity of the androgen receptor in prostate cancer cells without, at times, having an influence in the surrounding tumor milieu." (PMID 40647555, 2025). "Despite the development of multiple AR signaling inhibitors (ARSI, including abiraterone, enzalutamide, darolutamide, and apalutamide) that have improved the clinical outcome for patients with advanced disease, treatment resistance is inevitable and advanced prostate cancer remains fatal." (PMID 39787247, 2025). "Hematoxylin-eosin (HE) and immunohistochemistry (IHC) revealed prostate carcinoma with negative staining of androgen receptor (AR) and strong expression of NE markers, including SYN, CgA, CD56 and INSM1, indicating small cell neuroendocrine carcinoma (SCNEC) in 10 of 13 cores." (PMID 39926281, 2025). "Notably, an inactive AR signaling does not unleash IL-1β expression in all prostate cancer phenotypes." (PMID 39858071, 2025). "More importantly, they have recently been found to have a role in metastatic castration-resistant prostate cancer as well, thus indicating that these agents could have a role regardless of the androgen receptor status and dependence of the cancer cells." (PMID 40647555, 2025). "Amongthese drugs, Chloramphenicol is a broad-spectrum antibiotic knownfor its effectiveness against various severe bacterial infections.Darolutamide, a nonsteroidal androgen receptor antagonist, is utilizedin treating nonmetastatic, castration-resistant prostate cancer." (PMID 40094320, 2025).
prostate carcinoma (continued). "To investigate the role of FZD6 in prostate cancer progression, we used 2 shRNAs to knock down FZD6 in 3 representative human prostate cancer cell lines that highly express FZD6: the androgen receptor (AR) negative DU145, androgen-independent but AR-expressing C4-2B and LN95." (PMID 41286306, 2025). "RXFP1 is expressed in both AR positive and negative prostate cancer and prostate cancer cell lines." (PMID 41347146, 2025). "In addition to the comprehensive characterization of our platform, we validated our MPS as a model for studying bone metastasis in prostate cancer, where we created a 3D culture with prostate cancer spheroids (DU-145, LNCaP, and LAPC4) representing different AR statuses." (PMID 40596459, 2025). "Additionally, DNPC is a kind of prostate cancer that is independent of both androgen receptor and neuroendocrine signals." (PMID 39976818, 2025). "Furthermore, one of the major 4HNE protein adducts with a molecular weight of around 55 kDa was increased in all 3 prostate cancer cell lines regardless of the status of androgen receptor among them." (PMID 41008967, 2025). "We envisioned that negative feedback in prostate cancer cells, initiated by AR induction of PARP7, could temporally regulate the effects of circulating and tumor-derived androgens and potentially affect disease progression." (PMID 40681873, 2025). "In particular, AURKA may serve as a compensatory pathway to support tumor activity after AR inhibition in prostate cancer, a complex mechanism not seen in other tumors." (PMID 40718709, 2025). "Furthermore, prostate cancer organoids and their corresponding tissues were analyzed by immunohistochemical profiling of Cytokeratin 5/6 (CK5/6), Cytokeratin 8 (CK8), and Androgen Receptor (AR)." (PMID 41463218, 2025). "Blocking androgen receptor activation with androgen synthesis inhibitors could also promotes the apoptosis of prostate cancer cells in both androgen receptor positive and negative prostate cancer cells." (PMID 40420092, 2025). "Interestingly, NXP800 demonstrated anticancer activity in AR-negative prostate cancer cell lines, suggesting that the antitumor activity of the drug is not only due to blocking AR signaling." (PMID 39787247, 2025). "Treatment options for advanced prostate cancer (PCa) are broadly categorized into radiotherapy, taxane-based chemotherapeutics and suppression of the androgen signaling axis via androgen deprivation therapy (ADT) and androgen receptor signaling inhibitors (ARSI)." (PMID 41327318, 2025). "Since c-Myc and PI3K regulate AR levels, while AR regulation was not the focus of this study, it remains to be studied how EphB4 may regulate AR in prostate cancer." (PMID 40044981, 2025). "These tests are also usually pan tumor and not prostate cancer specific and thus may not be designed to optimally detect all AR alterations or ETS rearrangements." (PMID 38383885, 2025). "Of note, the PC-3, Du145, and 22Rv1 cell lines represent models of advanced, androgen-independent prostate cancer with no androgen receptor (AR-null, PC-3, and Du145) expression or an androgen-insensitive AR variant (ARv7) co-expressed with a full-length AR (22Rv1)." (PMID 40407591, 2025). "Androgen receptor (AR) suppresses DPYSL5, and overexpression of DPYSL5 promotes prostate cancer cell plasticity via EZH2-mediated PRC2 activation, suggesting that the AR/DPYSL5/EZH2/PRC2 axis may act as a driver of treatment-induced neuroendocrine prostate cancer." (PMID 38238517, 2024).
prostate carcinoma (continued). "We used human breast cancer‐derived cells with high, low, and very low expression levels of AR, in addition to prostate cancer‐derived LNCaP and DU‐145 cells as a positive and negative controls to examine apoptosis caused by a synthetic peptide that targets ARs." (PMID 37903548, 2024). "In addition, as a downstream gene of the AR, PEX10 may involve in the ROS depletion, ferroptosis sensitivity and cellular senescence of prostate cancer and promote prostate cancer cell proliferation." (PMID 39097593, 2024). "However, we focused on understanding the role of E2F8 in regulating AR due to the lack of E2F8 studies in prostate cancer." (PMID 38605607, 2024). "In addition to AP-1, Janus kinase (JAK)/STAT signaling has the potential to crosstalk with GR in AR-negative prostate cancer." (PMID 39027480, 2024). "Interestingly, N-cadherin overexpression is increased with androgen receptor inhibition in prostate cancer cells, with no accompanying augmentation of mRNA levels for the EMT transcription factors that regulate mesenchymal protein expression." (PMID 39796673, 2024). "When combined with Enzalutamide, an androgen receptor inhibitor, SR48692 also reduced neuroendocrine differentiation and slowed tumor growth in prostate cancer xenografts, suggesting that targeting the NT system could delay castration-resistant prostate cancer progression." (PMID 39519199, 2024). "Therefore, we conducted WB validation for GPX4 and MBOAT2 simultaneously and found that AR indeed enhances MBOAT2 rather than GPX4 in prostate cancer." (PMID 39097593, 2024). "Here, we show the novelty of this manuscript, revealing that water extract of Astragalus membranaceus significantly exerts an apoptotic effect through the inhibition of the PSA and AR, specifically in AR-dependent LNCaP prostate cancer cells, not in AR-independent prostate cancers." (PMID 38474045, 2024). "Proteasomal degradation of TM4SF3, in contrast to AR and AR-V7, was unknown until our two recent studies, showing that MG132 can block TM4SF3 degradation in prostate cancer cells, and demonstrated TM4SF3 in vitro ubiquitination that is inhibited by association with either AR or AR-V7." (PMID 38410785, 2024). "Multiple studies found that menin promotes the growth of AR-negative prostate cancer cell lines." (PMID 39336822, 2024). "When we expressed AR-V7 in a novel AR-negative murine prostate cancer cell line, we found evidence for androgen signaling and transcriptional stimulation of extracellular matrix production and MAPK/ERK signaling, as well as suppression of chemokine gene signatures." (PMID 39591176, 2024). "In addition, the present study results confirmed that FTO down-regulation was linked to poor prostate cancer prognosis and FTO knockout in AR-negative PC-3 cells promoted cell proliferation and migration via EMT." (PMID 38384328, 2024). "Thus, the combined absence of both AR and FOXA1 likely contributes to the heightened levels of GR in AR-negative prostate cancer cells." (PMID 39027480, 2024). "Thus, these vaccines demonstrated the ability to elicit AR-specific and AR-V7-specific T cells responses in mice, which varied based on their genetic background and MHC-I repertoire, suggesting their potential utility against prostate cancer." (PMID 39591176, 2024). "We conducted an analysis of multi-omics data from TCGA and SRA databases, including AR ChIP-seq, transcriptomic, single-cell transcriptomic, lncRNA, SNV, CNV, DNA methylation, and clinical data of PCa patients to identify key gene sets related to prostate cancer." (PMID 38778150, 2024). "Notably, RECWAS identified 3 out of 18 AR peaks and 6 out of 32 H3K27ac peaks in the prostate cancer gold peak datasets, whereas CWAS identified none." (PMID 39099406, 2024).
prostate carcinoma (continued). "A scRNA-seq-based research found that a subpopulation of CRPC-like cells and a subpopulation of neuroendocrine cells independent of the AR signaling pathway, which share the exact origin as prostate luminal and basal cells, were present in primary prostate cancer tissues without endocrine therapy." (PMID 39655078, 2024). "Additionally, the study revealed that ALDH1A1 overexpression is associated with high expression of Polo-like kinase 3 (PLK3) in prostate cancer bone metastases, suggesting that ALDH1A1 regulates PLK3 through its interplay with AR and RAR-dependent transcription." (PMID 39796106, 2024). "Importantly, although probably independent of BAG-1 isoform function, Thio-2 suppressed AR signaling and other key prostate cancer signaling pathways to inhibit the growth of CRPC models." (PMID 38412481, 2024). "We observed in this study that treatment with HDACi and docetaxel resulted in increased migratory behavior in both AR-positive and AR-negative prostate cancer cells, indicating that these effects on cell migration in prostate cancer cells are not limited to only anti-androgens." (PMID 38254786, 2024). "Interestingly, also Notch pathway is regulated in prostate cancer; indeed, recent data show that it alters the correct signaling of both phosphoinositide 3-kinase (PI3K)/Akt pathway and AR pathway, which coordinate carcinogenesis, EMT, metastasis and cancer progression in this tumor type." (PMID 38216942, 2024). "Moreover, compound 18 showed potent activity against another prostate cancer PC-3 (androgen receptor negative) cells, with an IC50 value of 5.1 μM." (PMID 39852509, 2024). "Hence, androgen-induced interactions between AR and JUNB or ERF may confer growth inhibitory actions that are conserved across breast and prostate cancer contexts, but this requires future investigation." (PMID 38317241, 2024). "Assessment of 11 patient-derived melanoma cell lines showed that, while significantly lower compared to a prostate cancer cell line (LNCaP), 4 of the 11 cell lines (WM793, WM1366, IPC298, and A375) express detectable AR protein, regardless of mutation background or sex origin." (PMID 38326303, 2024). "However, these cellular assays indicated a differential mechanism of MA action in AR‐positive and AR‐negative prostate cancer cells." (PMID 38605607, 2024). "Furthermore, dependency on FGF signaling has been reported in a subset of castration-resistant prostate cancers characterized by limited or absent androgen receptor expression and non-NE features." (PMID 38897168, 2024). "One possible explanation could be due to the fact that AR-negative DU145 prostate cancer cells have been shown to respond to enzalutamide treatments through the glucocorticoid receptor (GR), encoded by NR3C1 gene." (PMID 38254786, 2024). "Additionally, none of the established cell lines did show prostate cancer specific characteristics., e.g., AR or solely luminal gene expression." (PMID 38704600, 2024). "The androgen receptor antagonist apalutamide (ARN) and the complex I inhibitor IACS-010759 (IACS) regulate the process of mitochondrial fission and fusion in prostate cancer, and the combination of the two can increase androgen-sensitive prostate cancer cell death and mitochondrial oxidative stress." (PMID 39609317, 2024). "We have used Raman spectroscopy to reveal complex mechanisms in disease-state switching in low-grade AR-negative prostate cancer, demonstrating molecular pathways for targeted arrest and disruption in difficult-to-treat tumorigenic prostate cancer at the earliest possible stage." (PMID 39455589, 2024). "Aberrant transcription in prostate cancer is not driven solely by AR activity but through the collaborative action of AR enhancers like those of HOXB13 and FOXA1 genes, which modify chromatin structure to facilitate AR and other factors in accessing cancer-specific binding sites." (PMID 39796635, 2024).